ATRX (ATRX chromatin remodeler)
Diseases named in the same sentence as ATRX in open-access papers (continued):
Sharing a sentence is not in itself a finding about the gene and the disease.
tumor (continued). "The withdrawal A (from a manual microdissection), showed a Ki-67 LI = 19.3%, tumour cells with a C250T pTERT mutation and nuclear ATRX immunoreactivity." (PMID 34573966, 2021). "The withdrawal B (from a manual macrodissection) had a Ki-67 LI = 13% and showed loss of ATRX expression in tumour cells that harboured a C228T pTERT mutation." (PMID 34573966, 2021). "Loss of ATRX staining in the tumor cells was seen in 2 cases and intact ATRX staining in the remaining cases." (PMID 34647024, 2021). "In PanNETs, there is a high ratio of inactivated to missense mutations in DAXX/ATRX, suggesting that they function as tumor suppressor genes." (PMID 35087762, 2021). "ATRX gene was mutated within a tumor that originated within the white matter of the parietal lobe, but its expression within the parietal lobe was not elevated." (PMID 34257334, 2021). "PDX1 presented hypermethylation and lower expression in tumours with mutations in the ATRX/DAXX/MEN1 genes (T2 and T3) than in wild-type tumours (T1)." (PMID 33536587, 2021). "For instance an animal model of ATRX-deficient GBM was created to show that loss of ATRX accelerated tumor growth rate and reduced median survival." (PMID 34830952, 2021). "Tumours in subgroup T2 harboured more mutations in ATRX, DAXX and MEN1 with recurrent loss/LOH across 11 chromosomes." (PMID 33536587, 2021). "After assessing tumor pathology, ATRX mutations correlated with poor differentiation status, tumor necrosis, and the ALT mechanism." (PMID 34069193, 2021). "Among the 23 ALT-positive cases with exome sequencing data in paired tumor/normal samples, ATRX mutations were found in six samples, and a SMARCAL1 mutation was identified in one case." (PMID 32984050, 2020). "In two of the five discordant IHC-positive cases where FM detected nonmissense mutations (a splice site alteration (splice site 54492A > G) and bi-allelic loss of ATRX), different tumor blocks were used by IHC and FM." (PMID 32118206, 2020). "We screened MEN1, DAXX and ATRX genes for mutations and we classified DAXX/ATRX mutated samples, those tumours which are mutated in either or both the genes." (PMID 33288854, 2020). "One study has shown that six of such genes show increased loss-of-function mutations in male tumor diseases (ATRX, CNKSR2, DDX3X, KDM5C, KDM6A, and MAGEC3)." (PMID 32629877, 2020). "Tumour progression occurs upon DAXX/ATRX mutations, coupled with ALT activation and a characteristic CNA profile." (PMID 33288854, 2020). "Although conserved ATRX loss was demonstrated by IHC in both tumor samples, targeted sequencing revealed different ATRX mutations (R1426* in the diagnostic specimen and R1302fs*44 in the recurrent, post-irradiation specimen)." (PMID 33153497, 2020). "Altogether, 23 of 28 (82.1%) ALT-positive samples showed loss of nuclear ATRX staining in tumor cells." (PMID 32984050, 2020). "Doxycycline-induced overexpression of MYCN in ATRX-mutant NB cell lines showed a marked loss of tumor cells." (PMID 33628735, 2020). "Intriguingly, tumour cells with ATRX loss and reduce rDNA repeat numbers demonstrate significantly increased sensitivity to the Pol I transcription inhibitor CX-5461." (PMID 31973211, 2020). "In predominantly non-metastatic and well-differentiated/intermediate grade PanNETs, however, loss of DAXX/ATRX by IHC correlated with higher tumor grade and stage, risk for metastasis, and worse survival." (PMID 31692857, 2019).
tumor (continued). "Together, these data demonstrate that although ATRX loss fosters genetic instability and increases tumor aggressiveness, it also improves the response to chemotherapy based on DSB damage." (PMID 31752169, 2019). "In one tumor (ID80) we identified a nonsense mutation in ATRX (p.Glu481*), however, only at a frequency of 5.4%." (PMID 31212687, 2019). "Taken together, our findings suggest that mutations of DAXX and ATRX are hallmarks of tumor progression, and that they can occur rarely in panNETs ≤2 cm with pathologically-evident malignant potential." (PMID 31819132, 2019). "ALT and DAXX/ATRX loss have been correlated with higher tumor stage and grade and are therefore considered a late event in PanNET tumorigenesis." (PMID 30657883, 2019). "As such, our work has important implications for both the molecular pathogenesis of ATRX-deficient neoplasia, as well as the development of more effective drugs specifically targeting a palette of deadly tumors." (PMID 30808951, 2019). "From these studies, it is clear that the roles of DAXX and ATRX in cancer are complex and dependent on many factors, including the accompanying mutations, the tumor type, and alterations in histone variant expression." (PMID 29479426, 2018). "It has been associated with worse patient prognosis in some of these tumours, and it has been also correlated with loss of ATRX expression." (PMID 29751586, 2018). "Nonetheless, even in this case, the primary tumor and metastases shared molecular features including the same ATRX nonsense mutation accompanied by long telomeres and high expression of an RNA marker of cellular proliferation." (PMID 30062048, 2018). "In recurrent tumours, ATRX loss was more common in A, AA and sGBM than in rGBM; MGMT loss was not significantly different in A, AA, sGBM and rGBM." (PMID 29026176, 2017). "This was accompanied by a hotspot activating missense mutation in PTPN11, two inactivating frameshift mutations in the NF1 tumor suppressor gene, and an inactivating frameshift mutation in the ATRX tumor suppressor gene." (PMID 28699883, 2017). "In IDH1 mutant tumors, HGG7 harbored two ATRX alterations including a frameshift mutation exclusive to the primary tumor, while HGG6 acquired an additional ATRX missense mutation in the recurrence, in keeping with previous findings in IDH1 mutagenesis." (PMID 29084603, 2017). "In the H3/IDH1 mutant group, ATRX mutations were observed in 3 hemispheric tumor pairs: one pair with H3G34V (HGG5), and two with IDH1 R132H/S (HGG6, HGG7) mutations." (PMID 29084603, 2017). "The loss of DAXX or ATRX correlated with tumor stage and metastasis, reduced time of relapse-free survival and decreased time of tumor-associated survival." (PMID 28591701, 2017). "ATRX mutation was determined by the loss of protein expression in tumor cells as observed by immunohistochemistry." (PMID 28030632, 2016). "ATRX is frequently mutated in tumor cells with alternative lengthening of telomeres (ALT), and its loss has been shown to promote ALT." (PMID 27634879, 2016). "This included four out of five ATRX mutation-positive tumors (80%) as well as the one DAXX mutation-positive tumor." (PMID 26891131, 2016). "It is apparent then that the loss of ATRX in an ALT tumour cell line leads to an increase in replication fork stalling." (PMID 26143912, 2015).
tumor (continued). "Mutations in ATRX have recently been identified in tumours which maintain their telomeres by a telomerase independent pathway involving homologous recombination thought to be triggered by DNA damage." (PMID 24651726, 2014). "Recently, large-scale genome sequencing efforts have identified ATRX mutations and deletions in a range of tumor types, including glioblastoma multiforme, neuroblastoma and pancreatic neuroendocrine tumors." (PMID 24834375, 2014). "These alterations appear to result in loss of functional ATRX, suggesting that ATRX acts as tumor suppressor." (PMID 24834375, 2014). "Mutations in ATRX have been identified in multiple tumor types and appear to cause alternative lengthening of telomeres (ALT), a presumed precursor to genomic instability." (PMID 23104868, 2012). "Intriguingly, the distribution of ATRX mutations tracked with specific diagnostic and molecularly defined tumor subclasses." (PMID 23104868, 2012). "A loss of ATRX expression could likewise promote genomic instability and thus facilitate tumour initiation." (PMID 41472189, 2025). "ATRX (alpha thalassemia intellectual disability syndrome X-linked) is a tumour-suppressor gene encoding for a chromatin remodelling and transcriptional regulator protein intercalated in key molecular pathways, such as the regulation of chromatin state, gene expression, and DNA damage repair." (PMID 40870498, 2025). "We hypothesized that ATRX mutations could modulate the expression of genes involved in anti-tumor responses, including immune checkpoint-related genes and components of the tumor TIME." (PMID 40495762, 2025). "Thus, the most commonly mutated genes in sporadic GEP‐NETs are MEN1, death‐domain‐associated protein (DAXX), and ATRX Chromatin Remodeler (ATRX), occurring in 40%, 25%, and 17% of tumours, respectively." (PMID 39579056, 2025). "We further demonstrated that exposure to hypoxia (with consequent generation of ROS) was also able to precipitate ALT-pathway induction in cells lacking ATRX, and we present evidence that ATRX-mutant LGG have gene signatures more strongly associated with hypoxia than ATRX-wildtype LGG tumours." (PMID 39921567, 2025). "However, stratified analysis according to IDH mutation status found that a low proportion of ATRX+ tumor cells indicates poor prognosis in IDH mutation patients." (PMID 40264576, 2025). "Mutations of DAXX and ATRX appeared to correlate with loss of nuclear immunolabelling, as seen in PanNENs, although exceptions may occur depending on the tumour type." (PMID 41472189, 2025). "Changes in CCDC69 expression resulting from ATRX mutation may influence tumor progression and immune responses in LMS tissue." (PMID 40495762, 2025). "ATRX mutations also influence immune pathways by modulating the tumor microenvironment, promoting immune cell infiltration while upregulating immune checkpoint proteins like PD-L1 and PD-L2, which may facilitate immune escape." (PMID 39910169, 2025). "Additionally, a Genetically Engineered Mouse Model (GEMM) expressing the H3.3G34R mutation and ATRX loss in Nestin + progenitor cells in neonatal mice generated tumours expressing early neuronal markers Stmn2, Nefm and Nefl." (PMID 40986124, 2025). "However, the occurrence of ATRX mutations can cause changes in the molecular and clinical aspects of tumor characteristics." (PMID 40286729, 2025). "Mutations in ATRX have been identified in multiple tumor types." (PMID 40103938, 2025).
tumor (continued). "ATRX (alpha-thalassemia mental retardation X-linked) is known to regulate essential processes such as chromatin remodeling, gene expression, and DNA damage repair, thereby contributing to genomic stability and exerting potent tumor-suppressive functions." (PMID 40495762, 2025). "ATRX mutations, for instance, are often associated with alternative lengthening of telomeres, which contribute to tumor growth and may correlate with specific tumor subtypes and patient outcomes." (PMID 39767571, 2024). "ATRX is known to function as a tumor suppressor, with mutations identified in many cancers." (PMID 39479502, 2024). "We found MYCN amplifications in 23 tumors (20%), rearrangements affecting the TERT locus in 19 tumors (17%) and ATRX mutations in 12 tumors (10%), comprising 7 focal deletions, 4 missense or nonsense mutations and one tumor affected by a structural rearrangement (NBL54)." (PMID 39635126, 2024). "ATRX mutations may contribute to a tumor microenvironment that favors the expression of drug resistance genes, including ABCG2." (PMID 38542090, 2024). "Analysis of the tumor samples revealed loss of ATRX expression in both surgical specimens, suggesting that ATRX may be a useful biomarker for the early identification of aggressive pituitary tumors." (PMID 39108605, 2024). "ATRX functions as a tumor suppressor and thus, loss-of-function mutations at the ATRX locus reduce H3.3 deposition, and facilitate telomeric instability and subsequent homologous recombination to initiate telomerase-independent alternative lengthening of telomeres (ALT)." (PMID 38525424, 2024). "We reasoned that this discrepancy might simply reflect the lower tumor size of ATRX-deficient xenografts, and indeed by immunohistochemistry, we found higher levels of CD45 and F4/80 cell labeling in both Atrx KO-A and KO-B tumors than in CRISPR controls." (PMID 38272925, 2024). "IHC analysis confirmed IDH1 R132H expression and ATRX loss in the nuclei of tumor cells." (PMID 39256867, 2024). "This suggests that ATRX may be positively associated with tumor stage and metastasis, reduced relapse-free survival time, and tumor-associated survival time." (PMID 38884081, 2024). "Our study found that ATRX mutations showed preferential memory performance on the MOCA test, which may also be due to ATRX mutations favoring a slower tumor growth rate." (PMID 38315329, 2024). "Mutation of ATRX was a common phenomenon in numerous tumours and contributed to tumour development." (PMID 38126976, 2023). "Both K27M and G34R altered tumours could exhibit ATRX loss or retention, though ATRX loss was more likely in our histone G34R altered samples." (PMID 37665980, 2023). "The ATRX mutations were predicted loss of function variants and these tumors displayed evidence of elongated telomeres, as determined by Telseq analysis comparing tumor vs matched normal blood." (PMID 36604421, 2023). "Furthermore, a recent report noted that loss of ATRX promotes OS tumor through increased NF-κB signaling and integrin binding." (PMID 37511127, 2023). "In addition, a group of tumor suppressors that escape from X-inactivation have been implicated in cancer sex bias 30, our analysis did reveal higher expression of ATRX, DDX3X, KDM5C and KDM6A in female than male patients." (PMID 36118521, 2022). "Moreover, a recent study described the co-existence of NF1 germline mutations and ATRX somatic alterations in different tumours from NF1 patients." (PMID 36760809, 2022).
tumor (continued). "A recent large study involving 2500 matched tumor–control samples from 36 different tumor types suggests that whereas the telomere content of tumors with ATRX or DAXX mutations is increased, tumors with TERT modifications show a moderate decrease in telomere content." (PMID 35565379, 2022). "Furthermore, by using FISH technique, 19 tumor samples with ATRX/DAXX mutations were all found to have abnormal ALT levels." (PMID 36139607, 2022). "Although DAXX and ATRX have both independent and shared functions, the mutually exclusive pattern of mutations in PanNETs strongly implicates their shared function in tumor suppression." (PMID 35976056, 2022). "Shared biallelic NF1 inactivation was present in all three tumor pairs, as well as shared CDKN2A homozygous deletion and ATRX mutation in two tumor pairs each, thereby indicating these were initiating truncal events critical to gliomagenesis in the setting of NF1." (PMID 35945463, 2022). "ATRX is a tumor suppressor gene and encodes a member of the SWI/SNF family of proteins." (PMID 33678158, 2021). "ATRX is a novel tumor suppressor gene that encodes an SWI/SNF-like chromatin remodeling protein." (PMID 34422662, 2021). "Additionally, 18 tumor samples had both ATRX/DAXX truncating or other missense mutations and TERT alterations." (PMID 32024817, 2020). "However, tumours with truncating mutations in ATRX or DAXX showed the highest proportion of low-confidence chromothriptic events, suggesting a potential enrichment for a form of chromothripsis with few breakpoints in this group." (PMID 32385320, 2020). "Additionally, sequencing of the diagnostic and recurrent tumor specimens revealed different ATRX mutations, though both resulted in conserved loss of ATRX function." (PMID 33153497, 2020). "In addition, IDH1 mutation and low expression of ATRX and Ki67 showed marginally significant association with decreased tumor growth." (PMID 32388499, 2020). "We identified single-nucleotide variations, small indels, and other somatic mutations in the coding region of ATRX via custom capture and Illumina sequencing using probes spanning the entire ATRX locus and whole-exome sequencing of 828 germline and tumor samples." (PMID 32060267, 2020). "However, the full impact of ATRX deficiency on tumor initiation and evolution almost certainly includes other molecular mechanisms." (PMID 30808951, 2019). "Second, although mutations of DAXX/ATRX critically enhance tumor malignancy, tumor relapse and metastasis formation may also occur in the setting of tumors with an intact DAXX/ATRX machinery, as observed in our study as well as in others." (PMID 31819132, 2019). "One tumor (ID61) had a missense variant in ATRX (p.(Asn53His)) at an allele frequency of 25%." (PMID 31212687, 2019). "However, in ATRX-wildtype tumours, the mechanisms underlying ALT activation remain to be elucidated." (PMID 29751586, 2018). "The tumor samples were screened for TERTp and ATRX/DAXX mutations, and TERT rearrangements." (PMID 29312603, 2017). "The suggestion that ATRX/DAXX defects leading to ALT occurs only in a later stage is compatible with the fact that in hereditary-associated tumors there is an anticipation in the manifestation of the neoplasia." (PMID 27411289, 2016). "As inactive ATRX is associated with ALT-specific tumor features, it could, for example, be targeted by synthetic lethality approaches." (PMID 27602331, 2016). "To date, however, it is unclear as to whether mutations in ATRX act as a driver or passenger in the formation of such neoplasms." (PMID 26143912, 2015).